CPPED1 (calcineurin like phosphoesterase domain containing 1)
Description:
Protein phosphatase that dephosphorylates AKT family kinase specifically at 'Ser-473', blocking cell cycle progression and promoting cell apoptosis. May play an inhibitory role in glucose uptake by adipocytes.
Synonyms: CSTP1; FLJ11151
Tractability: Antibody: its Gene Ontology location is reachable by antibodies, with high confidence; the Human Protein Atlas places it where antibodies can reach. PROTAC: ubiquitination databases record sites on it; its protein half-life has been measured.
Gene: Protein-coding gene on chromosome 16 (12,659,799 to 12,803,887, reverse strand). Ensembl gene ENSG00000103381.
Subcellular location: Cytoplasm
Subcellular location (Human Protein Atlas): Cytosol; Plasma membrane
Pathways (Reactome):
Immune System: Neutrophil degranulation
Gene Ontology:
Molecular function: hydrolase activity; protein serine/threonine phosphatase activity
Cellular component: cytosol; plasma membrane; azurophil granule lumen; extracellular region; cytoplasm
Genetic constraint (gnomAD): Loss-of-function variants: 31 observed, 32.49 expected, observed/expected ratio (o/e) 0.95, 90% interval 0.72 to 1.29. The upper end of that interval is the gene's LOEUF score, 1.29, which puts it in group 5 of 6, group 1 being the genes least tolerant of losing a copy. Missense variants: 504 observed, 427.68 expected, observed/expected ratio (o/e) 1.18, 90% interval 1.1 to 1.27. Synonymous variants: 198 observed, 185.63 expected, observed/expected ratio (o/e) 1.07, 90% interval 0.95 to 1.2.
Homologues: Orthologues: chimpanzee CPPED1 (99% identical), macaque CPPED1 (95% identical), pig CPPED1 (83% identical), dog CPPED1 (83% identical), guinea pig CPPED1 (83% identical), mouse Cpped1 (79% identical), rabbit CPPED1 (73% identical).
Diseases named in the same sentence as CPPED1 in open-access papers:
CPPED1 is named in the same sentence as 10 diseases in open-access papers, as found by Europe PMC text mining. Sharing a sentence is not in itself a finding about the gene and the disease. The quoted sentences say what the papers report.
bladder cancer (3 papers, 2020 to 2024). "CPPED1 expression levels are down‐regulated in non‐invasive bladder cancer tissue, whereas overexpression is associated with regression in tumour size." (PMID 34009729, 2021). "Additionally, expression of CPPED1 is decreased in invasive bladder cancer and overexpression of CPPED1 delays progression of the cell cycle." (PMID 32520951, 2020). "Calcineurin‐like phosphoesterase domain‐containing protein 1 (CPPED1) dephosphorylates AKT1 at Ser473, thereby preventing cancer progression in bladder cancer." (PMID 34009729, 2021).
atherosclerosis (1 paper, 2016). A disease characterized by the build-up of fatty material and calcium deposition in the arterial wall resulting in partial or complete occlusion of the arterial lumen. "Five of eight proteins are Peroxiredoxin-1 (Prdx-1), superoxide dismutase (SOD1), haemopexin (HPX), 60 kDa heat shock protein (HSP60), and serine/threonine-protein phosphatase (CPPED1), all of which are related to lipid peroxidation and atherosclerosis." (PMID 27536279, 2016).
COVID-19 (1 paper, 2022). A disease caused by infection with severe acute respiratory syndrome coronavirus 2. "Neutrophil transcripts which are robustly expressed in the uninfected state, including anti-proliferation and pro-apoptotic genes (LST1, G0S2, CPPED1, BTG2, PMAIP1) and anti-inflammatory genes (AMPD2, SEC14L1, ZFP36), are significantly downregulated in COVID-19 patients." (PMID 36466858, 2022).
preeclampsia (1 paper, 2020). Preeclampsia is a hypertensive disorder of pregnancy that is characterized by new-onset hypertension with proteinuria presenting after 20 weeks of gestation, and depending on mild or severe forms may initially present with severe headache, visual disturbances, and hyperreflexia. "In comparisons of spontaneous preterm and elective preterm cases, when we removed cases with preeclampsia and infection from all preterm groups, CPPED1 expression levels were not affected." (PMID 32520951, 2020). "This suggests that CPPED1 mRNA levels are not significantly affected by preeclampsia or intraamniotic infection." (PMID 32520951, 2020).
type 2 diabetes (1 paper, 2020). "Furthermore, CPPED1 knockdown improves insulin-stimulated glucose uptake in adipocytes and there are type 2 diabetes–associated loci in the CPPED1 promotor region." (PMID 32520951, 2020).
tumor (4 papers, 2017 to 2024). "The other serine/threonine-protein phosphatase CPPED1 contains the R228Q mutation (CPPED-R228Q) and was identified from ID 261’s hepatic metastasized tumor tissue." (PMID 35982173, 2022). "CPPED1, also known as CSTP1, has been reported to be involved in blocking the cell cycle, promoting apoptosis, and suppressing tumor growth as a potential tumor suppressor." (PMID 30918060, 2019). "For example, CPPED1, GPRC5A, and TAGLN, recently reported to have tumor-suppressive function (57, –, 59), were significantly downregulated at both the mRNA and protein level." (PMID 30918060, 2019). "In the TCGA dataset, SLC25A37 was significantly upregulated in tumor tissues, while CPPED1 and KCNJ15 were significantly upregulated in adjacent non-tumor tissues." (PMID 38801430, 2024).
cancer (3 papers, 2006 to 2020). A tumor composed of atypical neoplastic, often pleomorphic cells that invade other tissues. "Earlier studies also showed that high levels of miR-371a-5 and low levels of CPPED1 are associated with striking functional effects in cancer tissue." (PMID 32520951, 2020).
CPPED1 also shares sentences with these, for which no sentence is quoted: Obesity (2 papers); breast carcinoma (1); infection (1).